CD93 (CD93 molecule)
Diseases named in the same sentence as CD93 in open-access papers (continued):
Sharing a sentence is not in itself a finding about the gene and the disease.
tumor (continued). "CD93 is also expressed in B cells (where it maintains antibody secretion) and in tumor-associated vessels, where it is correlated with a poorer survival." (PMID 37443812, 2023). "Many studies had shown that loss of CD93, either using siRNA knockdown of CD93 in ECs or investigating angiogenesis or tumor development in CD93 knockout mice, was associated with disruption of endothelial junctions and increased vascular permeability." (PMID 37660019, 2023). "It has been reported that CD93 is also associated with the infiltration of immune cells in tumor tissue and immunotherapy responses in cancer patients." (PMID 37443812, 2023). "In fact, the authors showed that IGFBP7 and CD93 expression was significantly increased in tumor-associated endothelial cells." (PMID 37443812, 2023). "CD93 expression levels in tumor blood vessels are associated with poor survival in patients with high-grade astrocytic glioma." (PMID 36389798, 2022). "Meanwhile, patients with a high CD93 mRNA level were associated with advanced tumor stage in BLCA and KIRP (p < 0.001)." (PMID 35265666, 2021). "Inhibition of integrin activation decreases angiogenesis and reduces tumor growth in several models, consistent with our observation of deficient integrin activation and decreased tumor growth observed in CD93–/– mice." (PMID 29763414, 2018). "The C-type lectin domain containing group 14 family members CLEC14A and CD93 are proteins expressed by endothelium and are implicated in tumour angiogenesis." (PMID 28671670, 2017). "Notably, CD93 is overexpressed in tumor-associated blood vessels, which is associated with poor prognosis and advanced disease stages." (PMID 40943530, 2025). "In CD93−/− mouse models, tumor vasculature showed increased permeability and reduced perfusion, suggesting that vascular dysfunction might partly underlie the anti-tumor effects of CD93 deficiency." (PMID 40943530, 2025). "Furthermore, CD93 is intricately linked to immune cell infiltration and immunotherapy, potentially acting as a new immune checkpoint within the tumor microenvironment (TME)." (PMID 40943530, 2025). "Taken together, these data indicate that CD93 deficiency increases vascular permeability in the lungs and contributes to the formation of a premetastatic niche that facilitates extravasation of circulating tumor cells and metastasis formation." (PMID 38441970, 2024). "Furthermore, elevated CD93 expression was correlated with more severe manifestations of tumor progression and strongly associated with poorer overall survival." (PMID 39190192, 2024). "Elevated CD93 is associated with immune cell infiltration in tumor tissues, low immunotherapy responses in cancer patients, tumor angiogenesis, poor prognosis, high tumor nodes, and metastasis (TNM) stages in several cancer types." (PMID 38999940, 2024). "In fact, CD93 expression was significantly higher in tumor-associated vessels." (PMID 37443812, 2023). "Moreover, a high CD93 expression was associated with tumor angiogenesis, immune cell infiltration, a poor prognosis and high TNM stage in many cancer types." (PMID 37443812, 2023). "In fact, CD93 is highly expressed in tumor-associated vessels and its presence correlates with a poor prognosis, poor immunotherapy response, immune cell infiltration and high tumor, node and metastasis (TNM) stage in many cancer types." (PMID 37443812, 2023). "Our results evaluated the connection between CD93 expression and prognosis, tumor mutation burden (TMB), microsatellite instability (MSI), immune checkpoints, TME, immune cell infiltration, and immune-related genes, providing supportive evidence of its vital role in the process of cancer." (PMID 35242761, 2022). "Tumor-associated myeloid cells exhibited higher transcriptional expression of molecules linked to the “find me” (G2A), “eat me” (CD93, TIM1, SCARF1, SLC2A1, GAS6, TREM2, AXL, C1QA), and downstream processing (NR1H3, ATG7, PPARG, ABCA1, PPARD, DOCK180) phases of efferocytosis." (PMID 36439171, 2022).
tumor (continued). "Furthermore, both the percentages and numbers of B220+CD93+ immature B cells were increased, whereas B220+CD93-CD21intCD23+ follicular B cells were decreased in tumor-bearing IDO deficient mice compared with naïve IDO deficient mice." (PMID 34867973, 2021). "Moreover, CD93 presented a robust correlation with immune modulators and immunotherapeutic markers [e.g., tumor mutation burden (TMB) and microsatellite instability (MSI)]." (PMID 35265666, 2021). "However, CD93-deficiency is associated with increased permeability, while endosialin expression in pericytes promotes intravasation of tumor cells and metastatic dissemination, indicating opposite roles in regulating vascular integrity." (PMID 31690961, 2020). "Interestingly, dextran leakage was further increased in lungs isolated from CD93-deficient mice subcutaneously injected with HCmel12 after 3 days from the tumor inoculation, indicating that CD93 deficiency promotes the formation of a premetastatic niche in the lungs." (PMID 38441970, 2024). "MMPs are upregulated in the tumor tissues and promote tissue colonization by metastatic cells; therefore, we asked whether the increased incidence of lung metastases observed in CD93–/– mice was associated with MMP9 upregulation." (PMID 38441970, 2024). "Moreover, Pearson association analyses indicated that CD93 was positively correlated with immunosuppressive subsets such as tumor-associated macrophages (TAMs), regulatory T lymphocytes (Tregs), and myeloid-derived suppressor cells (MDSCs) among those two datasets." (PMID 36006582, 2022). "Interactions with tissue stem cells through the Col1a1/Cd93, Col1a1/Itga5, Fn1/Plaur and Itgb1/Vcan pathways underscore the critical role of the monocyte-macrophage system in tumour immunosurveillance and immunomodulation." (PMID 40046334, 2025). "They observed upregulated CD93 in tumor tissues compared to normal tissues and downregulated soluble CD93 in patient plasma compared to healthy individuals." (PMID 40943530, 2025). "CD93 was shown to contribute to chemotherapy and immunotherapy resistance by enhancing tumor cell stemness, reducing immune cell infiltration, and inducing T-cell exhaustion." (PMID 40943530, 2025). "Antigen-pulsed engineered DCs induced significantly higher IFN-γ secretion and tumor cell killing than single-gene DCs, indicating the requirement of CD93, CD40L, and CXCL13 combination for optimal T cell activation and antitumor effects." (PMID 40733726, 2025). "Multiple studies have examined biopsy samples from cancer patients to explore the role of CD93 in tumor progression." (PMID 40943530, 2025). "Dysregulated expression of tumor suppressor molecules such as CD93 and its ligand IGFBP7 contributes to pathological tumor vasculature formation." (PMID 41281945, 2025). "Targeting the CD93 signaling pathway has the potential to improve tumor vascular function and enhance the efficacy of immunotherapy, making it a promising therapeutic target." (PMID 40943530, 2025). "IGFBP7 exhibits a dual role in cancer, exerting antitumor effects by inhibiting tumor cell growth and accelerating apoptosis, while also inducing a disordered tumor vasculature system by binding to CD93." (PMID 40943530, 2025). "In vitro studies indicated that tumor-induced monocytes upregulate CD93 via a glycolytic switch through the extracellular Erk pathway." (PMID 40943530, 2025). "We identified six cell types, including macrophages (PPP1R17), monocytes and neutrophils (FCAR, S100A12, CD93), tumor stem cells (CPZ), smooth muscle cell populations and epithelial cells (CSF3, TTC23L)." (PMID 41049004, 2025). "CD93, a C-type lectin-like protein, promotes immune cell infiltration and phagocytosis, critical for overcoming the immunosuppressive tumor microenvironment." (PMID 41295503, 2025). "These microbubbles demonstrated effective CD93 recognition and accumulation in CD93-rich tumor areas both in vitro and in vivo." (PMID 40943530, 2025).
tumor (continued). "Similar patterns were observed in intra- and extraocular tumor vessels, whereas normal choroidal vessels exhibited weak CD93 staining." (PMID 40943530, 2025). "The positive correlation between CD93 and M2 macrophages suggests an immunosuppressive role in the tumor microenvironment." (PMID 40943530, 2025). "Anti-CD93 not only inhibits tumor angiogenesis but also enhances CCL21 secretion by pleural mesothelial cells (pMCs), making it more effective than VEGF receptor blockers." (PMID 40943530, 2025). "Targeting CD93 on monocytes enhanced CD8+ T cell infiltration and activation, increasing tumor susceptibility to anti-PD-1 therapy in mice." (PMID 40943530, 2025). "In vitro and in vivo preclinical models exploring the roles of CD93 in angiogenesis, tumor progression and metastases build upon the foundation of our current mechanistic understanding of CD93." (PMID 38468017, 2024). "Tamoxifen treatment in CD93–/iECKO resulted in an improved CD93 gene deletion in the retina vasculature and an up to 75% decrease in CD93 expression in HCmel12 tumor vessels in CD93–/iECKO mice (respectively)." (PMID 38441970, 2024). "TEV-derived miR-5110 promotes CCL21 secretion by downregulating pMC CD93, whereas C1q, increasing in tumor individuals, suppresses CD93-mediated CCL21 secretion." (PMID 38250037, 2024). "A significant increase in CD93 expression is observed in tumor tissues compared to normal tissues in many cancers, including HCC." (PMID 38999940, 2024). "CD93 is mainly expressed in the tumor vessels in murine cancer models, but can also be expressed by some subtypes of hematopoietic cells." (PMID 38441970, 2024). "Probably, tumor products stimulate Ccl21a mRNA expression in pMCs, which is inhibited by the upregulated CD93 signaling, leading to similar Ccl21a mRNA level observed under tumor conditions." (PMID 38250037, 2024). "More importantly, CD93 blockade not only alleviates tumor growth and invasion but also shifts the tumor microenvironment toward immune infiltration and enhanced anti-tumor responses." (PMID 39190192, 2024). "Due to the aggressiveness of this tumor model, the absolute majority of wild-type mice and all CD93–/– mice displayed lung metastasis 14 days after inoculation of LLC1 tumors." (PMID 38441970, 2024). "Our data indicate that CD93 participates in molecular networks that stabilize tumor vessels, including those that regulate VEGFR2 activation." (PMID 38441970, 2024). "Ligand interaction with CD93 appears to mediate its role in physiologic endothelial activity as well as tumor angiogenesis." (PMID 38468017, 2024). "CD93 is generally expressed in tumor endothelial cells in many types of primary tumors, but its expression pattern in metastases has not been evaluated." (PMID 38441970, 2024). "A significant reduction in the expression of the adherens junction protein VE-cadherin was observed by immunofluorescent staining in the HCmel12 tumor vessels of CD93–/– mice." (PMID 38441970, 2024). "Further multivariate Cox regression revealed that only higher tumor grades (HR = 1.77, P < 0.001) and higher CD93 expression (HR = 3.26, P < 0.001) were independent variables that significantly associated with overall survival." (PMID 39190192, 2024). "Immune-related genes known to promote cancer growth, tumor angiogenesis, and tumor metastasis were also positively correlated with CD93 upregulation." (PMID 38468017, 2024). "CLEC14a, along with CD93, is recognized as part of a “common angiogenesis signature” characteristic of primary tumor tissue from head and neck squamous cell, breast, and clear cell carcinomas." (PMID 38468017, 2024). "By contrast, only mild and rare expression of CD93 was found on some lymphocytes and tumor cells, respectively." (PMID 39190192, 2024). "The median survival of CD93–/– mice after resection of the primary tumor was 33 days as compared with 37 days in the wild-type group, consistent with an increased metastatic burden." (PMID 38441970, 2024).
tumor (continued). "In line with this, circulating tumor cells were more frequently detected in the blood of CD93–/– mice bearing subcutaneous mCherry-HCmel12 tumors as compared with the wild-type group." (PMID 38441970, 2024). "CD93-blocking antibodies (anti-CD93) inhibit lung tumor growth better than VEGF receptor-blocking antibodies because anti-CD93 inhibit tumor angiogenesis and promote CCL21 secretion from pMCs." (PMID 38250037, 2024). "CD93 and CLEC14A have overlapping binding sites in MMRN2, and appear to elicit similar responses in tumor vasculature upon deficiency." (PMID 38441970, 2024). "Despite the reduced primary tumor growth observed in CD93–/– mice, metastatic dissemination to the lungs was increased." (PMID 38441970, 2024). "Based on calibrated tumor purity, we confirmed that CD93 expression correlated significantly with most of the representative markers in a variety of immune cells in LIHC." (PMID 37483608, 2023). "Based on the BCLC system, CD93 expression was higher in patients with LIHC classified as stages A, B, and C, which suggested that there was a close correlation between CD93 expression and tumor progression." (PMID 37483608, 2023). "This study identified CD93 to be involved in tumor vascular dysfunction and revealed an approach to promote a favorable tumor immune microenvironment for therapeutic intervention." (PMID 36761750, 2023). "To explore the basic expression of CD93, we first analyzed the mRNA expression of CD93 expression levels between normal and tumor samples in datasets from TCGA database which revealed that a significantly increased expression was found in STAD." (PMID 36761750, 2023). "Sun and colleagues found that insulin-like growth factor binding protein 7 (IGFBP7), an extracellular matrix (ECM) protein present on tumor vasculature, interacts with CD93, contributing to an abnormal tumor vasculature." (PMID 37443812, 2023). "In particular, IGFBP7 is a protein positively and significantly correlated with CD93 that has been identified to be up-regulated in tumor blood vessels and able to promote vascular angiogenesis." (PMID 37483608, 2023). "In the combined datasets based on an integrated database of GTEx and TCGA datasets, CD93 expression was significantly upregulated in the tumor samples of STAD." (PMID 36761750, 2023). "Beyond that, the density of CD93+ cells in tumor regions was higher than in stomach regions (p = 0.0220)." (PMID 36761750, 2023). "Studies found that CD93 promoted endothelial cells β1 integrin activation during tumor angiogenesis and blockade of CD93 can promote tumor vascular maturation, improving drug delivery and immune microenvironment." (PMID 36690975, 2023). "CD93, as a promising prognostic biomarker, exerts its immunoregulation properties and potential possibilities for tumor immunotherapy in STAD." (PMID 36761750, 2023). "In this review, we focus on CD93 which expresses on vascular ECs.CD93 expression was high during tumor neovascularization but low in quiescent blood vessels." (PMID 37660019, 2023). "The results of Western Blot and Real-time PCR have demonstrated that CD93 was markedly upregulated in LIHC tumor tissues than in adjacent tissues." (PMID 37483608, 2023). "In vivo, the study showed that although damage to HSPCs was minimal, there was severe “on-target, off-tumor” injury due to the ubiquitous expression of CD93 on endothelial cells." (PMID 37330575, 2023). "In this review, we focus on CD93 that expresses on angiogenic tip ECs, and the tumor angiogenesis process that was impacted by CD93." (PMID 37660019, 2023). "In current paper, we observed the co-expression of CD93 on tumor and stromal cells based on bulk and large-scale single-cell sequencing and tumor chips." (PMID 36389798, 2022). "For example, MMRN2’s interaction with CD93 activates β1 integrin signalling, which leads to fibronectin fibrillogenesis and tumour angiogenesis." (PMID 35132992, 2022).
tumor (continued). "The interaction between the MMRN2 coiled-coil region and CLEC14A and CD93 plays a role in tumour angiogenesis." (PMID 35132992, 2022). "Since the abnormal vasculature is a critical pathological feature facilitating tumor outgrowth and metastasis, the blockade of CD93 has been proved to contribute to immunotherapy response." (PMID 35978433, 2022). "For instance, CD93 was recently found to improve tumor vascular functions to promote T-cell infiltration and antitumor immunity after blockade of its pathway." (PMID 35242761, 2022). "Supporting that, ECs are the primary cell type expressing CD93 revealed by published single-cell RNA sequencing datasets of multiple human tumor tissues." (PMID 35242761, 2022). "The transmembrane glycoprotein CD93 has been identified as a potential new target to inhibit tumor angiogenesis." (PMID 36353214, 2022). "CD93 is expressed by various cells, including endothelial cells, myeloid cells, and even tumor cells in scRNA-seq dataset (GSE148071)." (PMID 35939336, 2022). "Previous studies have reported that MMRN2 and CD93 colocalize in neoplastic tissues of different origins and are highly expressed during tumor angiogenesis, which is consistent with the fact that this molecule is deposited along blood vessels." (PMID 36106120, 2022). "At the same time, CD93 expression was closely related to tumor purity in ACC, BLCA, COAD, PAAD, and READ." (PMID 35242761, 2022). "CD93 also acts as an important component in glucometabolic regulation for tumor ECs of high glycolysis in GBM." (PMID 36006582, 2022). "The previous study has demonstrated the critical role of CD93 in tumor vascularization and upregulated CD93 in tumor vessels as a potential malignant biomarker in several cancers." (PMID 36389798, 2022). "A recent study found that upregulated CD93 in tumor vessels is essential for tumor angiogenesis in several cancers." (PMID 36389798, 2022). "The treatment of the B16 tumour with anti-CD93 antibody normalised tumour vasculature and suppressed tumour growth." (PMID 36077754, 2022). "To assess the association of CD93 expression and TME, we calculated the stromal, immune scores, ESTIMATE scores, and tumor purity in 33 types of cancer." (PMID 35242761, 2022). "Our present research systematically analyzed the characteristics of CD93 in tumor immunotherapy among 33 cancers." (PMID 36389798, 2022). "Many stromal cells expressed high CD93 levels in the tumor microenvironment of pan-cancer, such as endothelial cells, B cells, T cells, neutrophils, myeloid dendritic cells, macrophages, monocyte, and hematopoietic stem cell." (PMID 36389798, 2022). "As a marker of tumor vasculature, the Group XIV family member endosialin was shown to regulate tumor growth and CD93 is homologous in structure to it." (PMID 35242761, 2022). "The immune landscape of CD93 in the tumor microenvironment was analyzed using the SangerBox, TIMER 2.0, and single-cell sequencing." (PMID 36389798, 2022). "Representative immunohistochemistry (IHC) images displayed that the CD93 protein was mostly enriched in membranes and had low expression in normal tissues when compared with tumor tissues in the stomach, liver, and pancreas (respectively)." (PMID 35265666, 2021). "On the contrary, the expression of CD93 was higher in lower tumor stages than in higher tumor stages in KIRC (p < 0.001)." (PMID 35265666, 2021). "The results of gene set enrichment analysis (GSEA) showed that CD93 was correlated with tumor angiogenesis." (PMID 35265666, 2021). "We used the Tumor Immune Estimation Resource (TIMER2.0) database to explore the expression of CD93 in pan-cancer." (PMID 35265666, 2021). "The relationship between tumor mutation load (tumor mutation burden, TMB), microsatellite instability (MSI), and CD93 expression was studied in this research." (PMID 35265666, 2021).